FETUB (fetuin B)
Diseases named in the same sentence as FETUB in open-access papers (continued):
Sharing a sentence is not in itself a finding about the gene and the disease.
Hepatic steatosis (17 papers, 2014 to 2025). Steatosis is a term used to denote lipid accumulation within hepatocytes. "Accordingly, a weak association of weight loss-induced short- and long-term decline of Fetuin-B and estimates of liver steatosis (HSI) was revealed in our cohort." (PMID 34611132, 2021). "As such, fetuin B provides an example of how hepatic steatosis can be linked to the development of insulin resistance and thus the metabolic syndrome." (PMID 26978356, 2016). "Based on the obtained results, we can suggest that serum fetuin-B concentration could be proposed as a biomarker of NAFLD or could reflect the risk of development of liver steatosis in early stage in PCOS women." (PMID 31307012, 2019). "Fetuin-B, also a secreted hepatocyte factor, was upregulated in humans with liver steatosis and patients with type 2 diabetes, and it impairs insulin action in myotubes and hepatocytes and causes glucose intolerance in mice, while silencing of fetuin-B in obese mice improves glucose tolerance." (PMID 33777158, 2021). "Fetuin B is a hepatokine that is upregulated by hepatic steatosis in obese persons and increased in type 2 diabetes." (PMID 37291355, 2023). "Despite their similarity, fetuin-A and fetuin-B play different roles in the pathophysiology of fatty liver." (PMID 36293317, 2022). "Circulating fetuin-B concentrations are significantly elevated in non-alcoholic fatty liver disease, hepatic steatosis, type 2 diabetes mellitus and gestational diabetes mellitus." (PMID 35265678, 2022). "Recently, fetuin-B has been suggested as a crucial secreted hepatocyte factor linking hepatic steatosis to impaired glucose metabolism." (PMID 35265678, 2022). "Very recently, elevated hepatic Fetuin-B mRNA expression or circulating Fetuin-B levels were reported in type 2 diabetes and liver steatosis." (PMID 34611132, 2021). "Circulating Fetuin-B levels correlated significantly with estimates of obesity, hepatic steatosis as well as HOMA-IR, ISIClamp, FFASupp at baseline." (PMID 34611132, 2021). "FETUB is secreted by hepatocytes and is upregulated in hepatic steatosis, and impacts impaired glucose metabolism." (PMID 34462546, 2021). "It has also been shown that overnutrition in experimental mice results in hepatic steatosis, and this alters the hepatocyte protein secretion profile leading to increased secretion of fetuin B." (PMID 26978356, 2016). "Fetuin A and FETUB are hepatokines that are upregulated in the state of hepatic steatosis." (PMID 34462546, 2021). "In the context of such an effect of Fetuin-B on lipolysis, elevated Fetuin-B levels in obesity and fatty liver disease might represent a counterbalancing mechanism to attenuate further lipid storage." (PMID 34611132, 2021). "In human studies, it has been demonstrated that serum fetuin-B was increased in humans with liver steatosis, patients with T2D, women with gestational diabetes mellitus (GDM), as well as in patients with coronary artery disease, in comparison to healthy controls." (PMID 31307012, 2019). "Fetuin-B has been introduced as a hepatokine/adipokine, which is increased in hepatic steatosis and may be connected with glucose metabolism disturbances." (PMID 31307012, 2019). "Furthermore, using an “omics” approach with human liver samples showed that fetuin B levels were elevated in patients with liver steatosis and type 2 diabetes." (PMID 31258482, 2019). "The expression of fetuin-A and fetuin-B is both upregulated in the presence of hepatic steatosis in human, but their regulation of glucose homeostasis is different fetuin-A alters insulin signaling, while the fetuin-B mechanism may be related to glucose utilization." (PMID 36293317, 2022). "Although some previous studies indicated that both fetuin-A and fetuin-B belonged to the proteins attributed to the cystatin superfamily with shares of 22% sequence similarity, other studies revealed the differential effects of fetuin-A and fetuin-B as regards to the pathophysiology of fatty liver." (PMID 32326594, 2020).
Hepatic steatosis (continued). "Therefore, serum fetuin-B concentration could be proposed as a biomarker of NAFLD and might reflect the risk of development of liver steatosis at an early stage in PCOS women." (PMID 31307012, 2019). "Increased fetuin B in patients with NAFLD.Fetuin B is positively correlated to triglyceride (TG) levels, as well as hepatic steatosis." (PMID 39858445, 2025). "Even though these results seem beyond our understanding, previous studies have shown that there was a great positive linear relationship between the natural progression of fetuin-B in NAFLD and hepatic steatosis." (PMID 32326594, 2020). "We concluded that serum fetuin-B levels are higher in women with PCOS and are independently connected with HOMA-β and hepatic steatosis." (PMID 31307012, 2019). "Serum fetuin-B levels are higher in women with PCOS and are independently connected with HOMA-β and hepatic steatosis." (PMID 31307012, 2019). "We also presented a relationship between serum levels of fetuin-B and HOMA-IR, HOMA-β, as well as different indices of liver steatosis, that is, FLI, VAI and LAP in PCOS women." (PMID 31307012, 2019). "Serum fetuin-B has been shown in clinical investigations to be favorably correlated with indicators of adipose tissue inflammation, including IL-6 and TNF-α, as well as the degree of hepatic steatosis." (PMID 40868109, 2025).
type 2 diabetes (10 papers, 2017 to 2025). "Studies have shown that Type 2 diabetes and liver steatosis are associated with elevated levels of fetuin-B in both liver and circulating blood." (PMID 37759310, 2023). "Interestingly, some of the down-regulated proteins are known to participate in inflammation (mast cell protease-1, complement C3, T-kininogen 1), adipose tissue metabolism (3-ketoacyl-CoA thiolase B), and oxidative stress (peroxiredoxin-1), or related to steatosis and type 2 diabetes (fetuin-B)." (PMID 31258482, 2019).
Obesity (9 papers, 2019 to 2025). Accumulation of substantial excess body fat. "To further confirm the association between Fetuin B and leptin in obesity, we established a mouse model of diet-induced obesity." (PMID 35896788, 2022). "Our previous population-based study demonstrated a significant association between serum Fetuin B and body fat mass in an obese population, which indicates its potential in mediating obesity-related metabolic disorders." (PMID 35896788, 2022). "In obese women with PCOS, circulating Fetuin-B levels were higher than those in lean women, suggesting an essential association of Fetuin-B with obesity." (PMID 33061822, 2020). "Serum Fetuin B was positively associated with leptin in obesity." (PMID 35896788, 2022). "Therefore, our study identifies leptin-STAT3 as an upstream signalling pathway that activates Fetuin B and provides new insights into the pathogenic mechanisms of obesity-related metabolic disorders." (PMID 35896788, 2022). "Our study revealed that increased Fetuin-B level in obesity could be attenuated by dietary weight loss." (PMID 34611132, 2021). "The association between fetuin-B and obesity thus remains ambiguous." (PMID 34646426, 2021). "Hyperlipidemia and hyperinsulinemia are two characteristic features of obesity and may contribute to the IR-associated elevation of circulating Fetuin-B in obese women and those with PCOS." (PMID 33061822, 2020). "Another hepatokine we found elevated in the OBO group was Fetuin B, which is modulated through leptin–STAT3 signaling and is known to exhibit an association with leptin in the context of obesity." (PMID 40076884, 2025). "We further analysed the correlation between Fetuin B and three key obesity indices, BMI, WHR and BFM." (PMID 35896788, 2022). "Recently, the role of Fetuin B in obesity and its related metabolic disorders has been demonstrated." (PMID 35896788, 2022). "Based on previous studies focusing on obesity and insulin resistance, we first measured body fat, serum leptin and Fetuin B levels in mice fed a HFD or chow for 12 weeks." (PMID 35896788, 2022). "Taken together, these findings demonstrate that Fetuin B levels significantly increase with body fat and leptin levels and persist during the progression of obesity." (PMID 35896788, 2022). "In line with such an assumption, we confirmed data revealing a relationship of Fetuin-B to estimates of obesity, liver fat, whole body, and myocellular insulin resistance, even if this was not described in all cohorts." (PMID 34611132, 2021). "This raises the possibility that Fetuin B may be triggered by signals from expanding adipose tissue in obesity, such as, leptin." (PMID 35896788, 2022). "Furthermore, we noticed that FetuB mRNA was significantly increased in mice fed a HFD for 12 weeks HFD mice compared to control mice, which suggests a transcriptional upregulation of Fetuin B in obesity." (PMID 35896788, 2022). "Thus, the correlation between BFM and Fetuin B identified in the present study further supports the notion that BFM is a more convincing indicator for obesity-related metabolic risks." (PMID 35896788, 2022). "The decrease of Fetuin-B correlates with improvement of estimates of obesity (BMI (r = 0.337; p = 4.2 × 10−5), fat mass (r = 0.281; p = 0.002), waist circumference (r = 0.262; p = 0.002)), ΔHSI (r = 0.179; p = 0.034), whole body (ΔHOMA-IR) as well as adipose insulin sensitivity (ΔFFASupp)." (PMID 34611132, 2021). "However, whether FXR or Foxo1 is involved in activating Fetuin B in the context of obesity requires further investigation." (PMID 35896788, 2022). "However, the precise mechanisms that trigger Fetuin B in obesity remain unclear." (PMID 35896788, 2022). "According to our previous study, the serum protein levels of fetuin-B and ZAG are significantly elevated in obesity-resistant rats exposed to a high-fat diet." (PMID 31504048, 2019).
steatosis (8 papers, 2017 to 2024). Increased lipid within the cytoplasm of cells. "A hepatokine, FETUB, which is regulated by steatosis and causes glucose intolerance by modulating insulin-independent glucose metabolism and is upregulated in T2D patients, was also significantly downregulated after chiglitazar treatment." (PMID 38182717, 2024). "It has been found that more fetuin-B is secreted during steatosis in liver cells in in vitro experiments." (PMID 37811770, 2023).
diabetes (7 papers, 2018 to 2025). "Fetuin-A, a plasma glycoprotein structurally similar to fetuin-B, is known to play a role in metabolic regulation and is associated with the pathophysiology of diabetes mellitus." (PMID 40636369, 2025). "After excluding the confounding factors such as liver dysfunction and diabetes mellitus, our study found that the serum fetuin-B levels of patients with essential hypertension were higher than those of healthy controls." (PMID 37811770, 2023). "The same study also found that silencing the fetuin B gene improved glucose tolerance in obese mice; thus, suggesting that this protein plays a role in the pathogenesis of diabetes." (PMID 31258482, 2019). "There might be a complex interplay among fetuin-B, metabolic syndrome, and vascular complications, since diabetes and dyslipidemia participate in the pathogenesis of atherosclerosis and cardiovascular diseases." (PMID 35265678, 2022). "Fetuin-B is encoded by the FETUB gene, which has a chromosomal localization of 3q27.3 with eight exons, and mutations in this region have previously been confirmed to be prone to MetS and diabetes." (PMID 34646426, 2021).
dyslipidemia (7 papers, 2020 to 2025). "As is the case with fetuin A, elevation levels of fetuin B also occur in diabetes and metabolic syndrome." (PMID 41341131, 2025). "Levels of fetuin-B levels in patients with metabolic syndrome are by improvements in insulin sensitivity, with a positive correlation between fetuin B and oxidative stress." (PMID 41341131, 2025). "Fetuins are named for their role during fetal development, but research has found that Fetuin B (FETUB) is involved in dyslipidemia, metabolic disease, and insulin signaling in the heart." (PMID 38500750, 2024). "In addition, serum fetuin-B levels positively correlate with intrahepatic triglyceride content, providing evidence for a relationship between fetuin-B and dyslipidemia." (PMID 35265678, 2022).
Glucose intolerance (7 papers, 2016 to 2024). Glucose intolerance (GI) can be defined as dysglycemia that comprises both prediabetes and diabetes. "Fetuin B is a hepatokine known to cause glucose intolerance, and its reduction is associated with an improvement of the body’s ability to dispose of a glucose load." (PMID 34822574, 2021). "These authors have identified higher levels of fetuin-B in the altered hepatokine secretory profile of steatotic livers in obese patients, and have also experimentally demonstrated that fetuin-B impairs insulin sensitivity in myotubes and hepatocytes and causes glucose intolerance in mice." (PMID 27005620, 2016).
gestational diabetes mellitus (6 papers, 2019 to 2025). "Moreover, an increasing number of studies have focused on the association between Fetuin B in females and metabolism-related disorders, gestational diabetes mellitus and polycystic ovary syndrome." (PMID 35896788, 2022). "In human studies, circulating Fetuin-B levels were elevated in obese individuals, patients with gestational diabetes mellitus (GDM) and T2DM, and related to IR and insulin secretion." (PMID 33061822, 2020). "In addition, higher fetuin-B levels have been observed in women with gestational diabetes, indicating its broader involvement in metabolic regulation." (PMID 40636369, 2025). "Several case-controlled and cross-sectional studies have reported that serum fetuin-B levels are markedly elevated in patients with nonalcoholic fatty liver disease, T2DM, gestational diabetes mellitus, and polycystic ovary syndrome." (PMID 34646426, 2021). "It has also been reported that in comparison with healthy controls, fetuin-B levels are substantially increased in patients with nonalcoholic fatty liver disease, T2DM, polycystic ovary syndrome, and gestational diabetes mellitus." (PMID 34646426, 2021).
female infertility (5 papers, 2015 to 2025). Diminished or absent ability of a female to achieve conception. "In addition, fetuin-B has been recently identified as the inhibitor of ovastacin, and genetic ablation of fetuin-B causes premature ZP hardening and, consequently, female infertility." (PMID 26633308, 2015). "To date, the variants and point mutations in fetuin-B deposited in the databases have not been linked to female infertility." (PMID 40697826, 2025). "In vivo, the small amount of ovastacin seeping from cortical granules prior to fertilization is controlled by its endogenous inhibitor, the plasma protein fetuin-B, to prevent premature ZPH-induced female infertility." (PMID 40697826, 2025). "Fetub, knockout mice, however, do not display these defects, and instead show female infertility; and mammalian Fetuin-B, unlike Fetuin-A, appears to function as a specific inhibitor of meprin and ovastacin metalloproteinases." (PMID 31989926, 2020).
polycystic ovary syndrome (5 papers, 2019 to 2025). A disorder that manifests as multiple cysts on the ovaries. "In women with polycystic ovary syndrome, an increased concentration of serum Fetuin-B was positively correlated with serum TNF-α, suggesting that Fetuin-B may potentially be related to low-grade inflammation." (PMID 37998747, 2023).
acute myocardial infarction (4 papers, 2022 to 2023). Necrosis of the myocardium, as a result of interruption of the blood supply to the area. "Fetuin-B levels may influence the risk of rupture of atherosclerotic plaques and thereby the risk of acute myocardial infarction." (PMID 35265678, 2022). "A previous study showed that the serum fetuin B expression level is higher in patients with acute myocardial infarction (AMI) than in those with stable angina." (PMID 37085769, 2023). "In the model of acute myocardial infarction, fetuin-B has been found to mobilize monocytes and macrophages, and the possibility of its influence on tumor-associated macrophages remains to be investigated." (PMID 37759310, 2023).
coronary artery disease (4 papers, 2021 to 2023). "Fetuin-B, a cytokine that regulates lipid metabolism, has recently been linked to cardiovascular diseases such as coronary heart disease." (PMID 37811770, 2023). "High fetuin-B levels are associated with the presence of coronary artery disease and acute coronary syndromes." (PMID 35265678, 2022). "Serum fetuin-B was elevated in patients with coronary artery disease and carotid artery stenosis, and correlated with the severity of coronary artery disease and carotid plaque burden." (PMID 37811770, 2023). "The serum level of fetuin-B, the protein encoded by the FETUB gene, is increased in patients with coronary artery disease." (PMID 37085769, 2023). "Zhu and other scholars also found that the content of fetuin-B was related to the severity of vascular diseases and speculated that fetuin-B might lead to the occurrence and development of coronary heart disease through inflammation." (PMID 37811770, 2023). "Finally, fetuin-B also negatively impacts metabolism because its serum level is higher in patients with coronary artery disease, especially in those with the acute coronary syndrome, and it still positively correlates with LDL-c levels." (PMID 33807959, 2021).